KLRK1 (killer cell lectin like receptor K1)
Diseases named in the same sentence as KLRK1 in open-access papers (continued):
Sharing a sentence is not in itself a finding about the gene and the disease.
adenoma (1 paper, 2017). A neoplasm arising from the epithelium. "Adenomas (20% of Klrk1+/+ versus 23.5% of Klrk1−/−) and nodules (6.7% of Klrk1+/+ versus 5.9% of Klrk1−/−) accounted for the tumours in the remaining mice, with similar incidence levels in both genotypes." (PMID 28128200, 2017).
allergic asthma (1 paper, 2018). A asthma with a basis in a pathological type I hypersensitivity reaction. "The finding that administration of anti‐NKG2D does not inhibit HDM‐mediated allergic asthma contrasts with earlier research that used mice genetically deficient for NKG2D (Klrk1−/−)." (PMID 29444897, 2018).
gram-negative bacterial infections (1 paper, 2020). Infections caused by bacteria that show up as pink (negative) when treated by the gram-staining method. "As markers GPR84, KLRK1, and TDRD9 were not represented in dataset E-GEOD-6269 (Affymetrix chip HG-U133A), interaction profiling of these genes was omitted from the gram-positive and gram-negative bacterial infection group dataset." (PMID 32318053, 2020).
head and neck squamous cell carcinoma (1 paper, 2023). A squamous cell carcinoma that arises from any of the following anatomic sites: lip and oral cavity, nasal cavity, paranasal sinuses, pharynx, larynx, and salivary glands. "The expression level of KLRK1 in tonsil cancers was significantly higher than in other head and neck squamous cell carcinomas." (PMID 37565867, 2023).
laryngeal carcinoma (1 paper, 2023). Carcinoma that arises from the laryngeal epithelium. "In laryngeal cancer, the expression level of KLRK1 was lower, and patients with low KLRK1 expression had a significantly worse prognosis than those with high KLRK1 expression." (PMID 37565867, 2023). "The expression level of KLRK1 was lower in laryngeal cancer than that in tonsil cancer." (PMID 37565867, 2023). "Therefore, we speculate that a possible immune evasion mechanism in laryngeal cancer is that tumor cells inhibit the low expression of KLRK1 by producing soluble NKG2DLs, and that a lower level of soluble NKG2DLs can lead to immune evasion." (PMID 37565867, 2023). "Therefore, we conducted an analysis to examine the relationship between the expression levels of KLRK1 and its ligands ULBP1-3 in patients with laryngeal cancer." (PMID 37565867, 2023). "In tonsil and laryngeal cancers, the immune escape mechanism mediated by KLRK1 and its ligands ULBP1-3 may competitively inhibit KLRK1, owing to insufficient expression/immune cell infiltration of KLRK1 or sufficient secretion of soluble NKG2DLs by tumor cells." (PMID 37565867, 2023).
larynx cancer (1 paper, 2023). A primary or metastatic malignant neoplasm involving the larynx. "High expression of these ligands in HNSCC increased the risk of patient death, especially in tonsil and larynx cancers, and their expression was negatively correlated with KLRK1 expression." (PMID 37565867, 2023).
steatosis (1 paper, 2023). Increased lipid within the cytoplasm of cells. "We found a striking reduction in the level of fibrosis in livers of Klrk1-/- mice compared to wild type C57BL/6J (WT) controls, whereas steatosis was not greatly affected." (PMID 37774007, 2023).
tonsil (1 paper, 2023). "In this context, we analyzed the prognostic relationship between the expression levels of KLRK1 and ULBP1-3 in tonsil cancers." (PMID 37565867, 2023).
tonsil cancer (1 paper, 2023). A primary or metastatic malignant neoplasm that affects the tonsil. "The expression levels of KLRK1 vary greatly between different types of cancer, with higher levels observed in tonsil cancer than in other types of cancer." (PMID 37565867, 2023). "In tonsil cancer, tumor cells already showed high expression of KLRK1, and patients with high expression of KLRK1 had a significantly better prognosis than those with low expression of KLRK1." (PMID 37565867, 2023). "KLRK1 expression significantly correlated with pT stage, HPV infection status, and tonsil cancer." (PMID 37565867, 2023).
tumor (1,468 papers, 2004 to 2026). "We previously reported that Apcmin/+ mice deficient for Klrk1 (Apcmin/;Klrk1−/−) survive longer than Apcmin/+;Klrk1+/+ mice and displayed a lower tumor burden." (PMID 36980678, 2023). "Association of KLRK1 expression with stage, T classification, N classification, M classification, residual tumor and vital status was evaluated." (PMID 35132098, 2022). "High tumor expression of KLRK1, more commonly known as NKG2D, was strongly associated with enhanced BLCA patient prognosis." (PMID 34858395, 2021). "Numerous reports have provided solid evidence for the importance of NKG2D in tumor surveillance and show that Klrk1−/− (the gene encoding NKG2D) mice are more susceptible to tumor development than control mice." (PMID 32052406, 2020). "One of the receptors responsible for the activation of the NK cells, NKG2D (NCBI symbol KLRK1) receptor, is implicated in interaction of NK cells with senescent cells during tumorigenesis and tumor therapy." (PMID 26878797, 2016). "Additionally, Cluster 5 in the tumor exhibited elevated expression of effector genes, such as Gzmb, Ifng, and Klrk1, linked to cytotoxic T cell functions." (PMID 40229241, 2025). "Finally, high tumor expression of transcripts encoding the activating NK cell receptors, KLRK1 and the CD160–TNFRSF14 receptor–ligand pair, was strongly correlated with the IL-2-expanded NK cell phenotype and improved BLCA prognosis." (PMID 34858395, 2021). "So there might be a connection between the KLRK1 and tumor-associated neutrophils (TANs)." (PMID 39575432, 2024). "The results showed that after stimulation with BLMP1/2A cells or T-ALL tumor cells, the expression of Klrk1 and Cd244 was significantly higher in CD8+ T cells from GCB-LMP1/2A mice compared to the control group." (PMID 40534857, 2025). "Compared to the BLCA tumour-adjacent normal tissues, tumour expression of transcripts encoding CD2, KLRK1, and NCR2 were higher." (PMID 39877370, 2024). "ITGAE is associated with a group of genes that have a cytotoxic function in CD8 cytotoxic T cells (CTSW, GNLY, NKG7, PRF1, GZMB, KLRK1) up-regulated in the tumor, identifying resident CD8 T cells in the tumor to have a highly cytotoxic and activated phenotype." (PMID 39548591, 2024). "DMBA3-4 tumor rejection persisted in Ifng–/– (IfngKO); Klrk1–/– (Klrk1KO); Sting–/– (StingKO); Ifnar1–/– (Ifnar1KO); Ticam1–/–,Myd88–/– (Ticam1KO Myd88KO); and Ncr1iCre,ROSADTR mice." (PMID 37843274, 2023). "This outcome was achieved by targeting tumor cells in laboratory settings and living organisms using NKG2D or KLRK1 (Killer Cell Lectin-Like Receptor K1), an activating receptor." (PMID 37987364, 2023). "Strikingly, our findings showed that the lower the tumor T grade, the higher the expression level of KLRK1 and the intensity of immune cell infiltration." (PMID 37565867, 2023). "KLRK1 is involved in regulating infection and tumor growth due to the frequent expression of its ligands on primary tumor cells." (PMID 36874133, 2023). "Tumor cells had the ability to secrete soluble NKG2DLs, which compete with KLRK1 on the immune cell surface." (PMID 37565867, 2023). "NKG2D (encoded by the killer cell lectin-like receptor subfamily K, member 1, or KLRK1 gene) is a C-type lectin receptor and a major activating immunoreceptor involved in tumor immune surveillance." (PMID 37143070, 2023). "The ligands of KLRK1 are frequently expressed on primary tumor cells and KLRK1 was reported to play a role in the control of tumor and infection." (PMID 35132098, 2022). "Histological type (P < 0.001), T classification (P < 0.001), N classification (P < 0.001), radiation therapy (P < 0.001), residual tumor (0.001), stage (P < 0.001) and KLRK1 expression (P = 0.003) showed significant differences." (PMID 35132098, 2022). "Some studies have demonstrated the antitumor function of KLRK1, while some researchers argue that KLRK1 contributes to tumor growth in a model of inflammation-driven liver cancer." (PMID 35132098, 2022).
tumor (continued). "T classification (P < 0.001), N classification (P < 0.001), M classification (P = 0.029), residual tumor (P = 0.037), stage (P < 0.001) and KLRK1 expression (P = 0.016) showed significant differences for lung adenocarcinoma cancer." (PMID 35132098, 2022). "Natural killer group 2D (NKG2D, also known as CD314 and encoded by the gene KLRK1) is the best characterized NK cell activating receptor that recognizes tumor cells that express NKG2D ligands." (PMID 33718188, 2021). "BLCA tumors with high expression of KLRK1, which encodes the activating NKG2D receptor, had a much improved prognosis compared with BLCA patients with low tumor expression of KLRK1." (PMID 34858395, 2021). "DNA hypomethylation augments NK cell-mediated lysis by increasing NKG2D-ligand expression that allows recognition of tumor AML cells by NKG2D receptor (encoded by Killer Cell Lectin Like Receptor K1, KLRK1) on NK cells." (PMID 30692641, 2019). "Compared to Klrk1−/− mice, wild-type mice displayed reduced survival and increased tumor burden assessed according to three criteria: liver/body weight ratio, maximal tumor size, and tumor load." (PMID 30150983, 2018). "In DEN-treated Klrk1+/+ mice, we observed a two-fold increase in total Klrk1 transcript in surrounding tissues compared with control mice and tumour tissues." (PMID 28128200, 2017). "IL-6 and TNF-α were also more expressed within the Klrk1+/+ tumour demonstrating that NKG2D has a significant influence on the tumour microenvironment, boosting the production of key pro-inflammatory cytokines." (PMID 28128200, 2017). "This is supported by a significantly higher amount of perforin and granzyme B transcripts in Klrk1+/+ than Klrk1−/− liver tissue surrounding tumours." (PMID 28128200, 2017). "Necrotic areas were greater in Klrk1+/+ compared with Klrk1−/− mice and significantly correlated with a higher tumour burden." (PMID 28128200, 2017). "Among IFNγ-producing cells, CD8+T cells were the dominant source of IFNγ accounting for 56.8% of IFNγ+ lymphocytes within the tumour of Klrk1+/+ mice, while NK and NKT cells represented 9.8% and 8.1% respectively." (PMID 28128200, 2017). "The elimination of CD4+ FOXP3+ Treg cells by T cells expressing the chimeric Klrk1/NKG2D receptor in the ovarian tumor microenvironment inhibited tumor growth and increased survival in mice." (PMID 28220815, 2017). "CD3ɛ expression on CD8+T cell was reduced in all tissues from DEN-treated mice compared with AMC, the reduction being greatest on CD8+T cells localized in the surrounding tissue of tumour-bearing Klrk1+/+ mice." (PMID 28128200, 2017). "NKG2D, encoded by the KLRK1 gene, is expressed on both T cells and NK cells and plays an important role in tumour response." (PMID 26471184, 2015). "Analysis of our previously published RNA-Seq dataset, which includes various cell types found in OC ascites and omental metastases, showed selective expression of KIR2DL1, KIR2DL4, and NCR1 in tumor-associated NK cells (TANK), and KLRK1 and NCR3 in both TANK and tumor-associated T cells (TAT)." (PMID 39563446, 2024). "Smaller tumor tissues tend to have higher expression levels of KLRK1." (PMID 37565867, 2023). "The interaction between KLRK1 and its ligands in the tumor microenvironment is complex." (PMID 37565867, 2023). "Finally, the incidence of tumors, which was approximately 25% in livers of one-year SSD fed WT animals, was more than two-fold reduced in the livers of Klrk1-/- mice, as was the average tumor size at the time point of analysis." (PMID 37774007, 2023). "The expression of KLRK1 in tumor was lower than that in normal tissue." (PMID 35132098, 2022). "A number of other immune-stimulatory genes were also upregulated, including the gene encoding granzyme B (GzmB; Log2FC 2.74, FDR = 3.49e−09) and Klrk1 (Log2FC 1.15, FDR = 0.016), which encodes NKG2D, the major NK- and T-cell receptor for recognition and elimination of tumor cells." (PMID 35131874, 2022).
tumor (continued). "The expression of KLRK1 in tumor was lower than that in normal tissue (P < 2.2e−16)." (PMID 35132098, 2022). "In vitro studies indicated that KLRK1 inhibited tumor cell proliferation and migration." (PMID 35132098, 2022). "However, tumor cells evoke a range of mechanisms to evade KLRK1 surveillance system detection and impair the clinical benefits of immunotherapy in various cancers." (PMID 33549054, 2021). "Additionally, treatment with decitabine for 28 days increases natural killer (NK) cell-mediated lysis of AML cells and increases expression of the killer cell lectin-like receptor K1 (KLRK1) ligand on tumor cells." (PMID 34759824, 2021). "Our results show that high tumor abundance of the IL2NK phenotype and transcripts for the KLRK1, CD160, and TNFRSF14 receptors are associated with improved survival, whereas high tumor abundance of the SPANK and PDGFD transcripts is associated with poor survival." (PMID 34858395, 2021). "Notably, mice deficient for NKG2D (Klrk1−/−) were hyper-responsive, resulting in the superior control of MCMV infection and tumor growth." (PMID 32733432, 2020). "However, a drastic reduction in TRAIL-expressing NK cells (CD3− NK1.1+) within the tumour was evidenced in both Klrk1+/+ and Klrk1−/− mice." (PMID 28128200, 2017). "Indeed, compared with Klrk1−/−, tumours in Klrk1+/+ mice proved to express a substantially higher level of the cyclin-dependent kinase inhibitor CDKN1A (p21), a critical player in liver regeneration and hepatocarcinogenesis." (PMID 28128200, 2017). "In addition, of the mice that reached end point defined as 15 month of age, Klrk1+/+ mice displayed an increased tumour burden compared with Klrk1−/− mice." (PMID 28128200, 2017). "Additionally, the incidence of Klrk1+/+mice developing tumours with the highest IHC score (score 3) was mildly increased compared with Klrk1−/−mice (19% versus 11.1% for GS; 9.6% versus 3.7% for Glypican-3 and 19% versus 11.1% for HSP70 respectively)." (PMID 28128200, 2017). "Accordingly, Klrk1+/+ mice displayed larger size tumours compared with Klrk1−/− mice and increased tumour load, measured as the sum of tumour diameters for all visible tumours over 5 mm." (PMID 28128200, 2017). "Notably, Klrk1+/+ mice showed a significantly higher liver/body weight ratio, which positively correlated with the maximal tumour size." (PMID 28128200, 2017). "Nonetheless, most activated cytotoxic CD8+ T cells (human and mouse) share the expression of the natural killer group 2, member D receptor (NKG2D) encoded by Klrk1, which upon binding to RAE-1 or related ligands, induced on tumor cells, stimulates effector responses that are independent of TCR21." (PMID 28220815, 2017). "NKG2D, encoded by the KLRK1 gene, is one of the activating immunoreceptors found on CD8 T cells and NK cells, and its ligands are stress-inducible proteins, including ULBP1, that enable the recognition and lysis of tumour cells." (PMID 23478435, 2013). "We detected multiple NK cell family receptor encoding genes (e.g., KLRK1, NCR2, CD2, and CD160) which might be critical in mediating anti-tumour immune responses against BLCA because higher expression of these genes was associated with better patient survival probabilities." (PMID 39877370, 2024). "The overexpression of the KLRK1 gene, encoding the NKG2D receptor essential for NK cell-mediated tumor killing, which engages with MIC ligands selectively upregulated on stressed or tumor cells, underscores its role in modulating T cell responses and enhancing TCR activation." (PMID 39660132, 2024). "In contrast, killer cell lectin like receptor K1 (KLRK1; also known as NKG2D), CD226 molecule (CD226; also known as DNAM-1) and natural cytotoxicity triggering receptor 1 (NCR1; also known as NKp46) can bind to ligands on the tumour surface and activate NK cells, causing them to release cytotoxins." (PMID 39070147, 2024).
tumor (continued). "Among others, germline-encoded activating receptors, such as KLRK1 (also known as NKG2D) and the Natural cytotoxicity receptors (NCRs), such as NKp46 (NCR1), NKp44 (NCR2), and NKp30 (NCR3), can synergize to overcome inhibitory thresholds and evoke NK cell anti-tumor functions." (PMID 34539622, 2021). "Importantly, among HCC-bearing mice, a higher proportion of Klrk1+/+ than Klrk1−/− mice (50% versus 33.3%) displayed a grade 3 HCC — the most advanced lesion based on histology This phenotype confirms the advanced tumour burden (tumour size and liver/body weight ratio observed in Klrk1+/+ mice." (PMID 28128200, 2017). "Gene signatures associated with NK‐cell cytotoxicity and activation (Gzma, Prf1, Klrd1, Nkg7, and Klrk1) were markedly upregulated at high proportions of NK cells in nanoSTING@Mn combined with LLL on dLNs and Tumor, as compared to nanoSTING@Mn alone (bottom)." (PMID 41126739, 2026). "Simultaneously, SPP1 downregulated CD40LG, TNFSF15, TNFRSF13B, IL6R, KLRK1, and other immune stimulants, indicating that SPP1 played a role in the evasion of tumor immunity by controlling the immunosuppressive surroundings." (PMID 38329443, 2024). "Correlation analysis indicated positive associations of CD160 ligands such as TNFRSF14 and HLA-C, and NKG2D (KLRK1) ligands MICA and MICB with the tumour-infiltrating CD56bright NK and CD8+ TEM cells." (PMID 39877370, 2024). "Comparing T cell gene expression between treatments revealed a significant increase in Klrk1, Klrc2, Klrd1, Fasl, and Sema4a in CD4 T cells at the tumor site after HVJ-E/OX40 antibody injection." (PMID 39534532, 2024). "When comparing Apcmin/+;Klrk1+/+ with Apcmin/;Klrk1−/−, we observed a higher fraction of tumor-infiltrating IFNγ-high producing CD8+ T cells in Apcmin/+;Klrk1+/+ than Apcmin/+;Klrk1−/− mice." (PMID 36980678, 2023). "Specifically, Kyn inhibits expression of the natural cytotoxicity triggering receptor 1 (NCR1, also known as NKp46) and killer cell lectin like receptor K1 (KLRK1, also referred to as NKG2D) on NK cells resulting in impaired tumor-killing functions." (PMID 37876966, 2023). "Overall, the Dox + IL-2ic therapy enhanced the anti-tumor immune response in a CD8+ T cell-dependent manner and induced large numbers of KLRK1+ CD8+ T cells." (PMID 36705564, 2023). "A substantial part of these KLRK1+ CD8+ T cells, especially in the tumor, were bona fide KILR cells as shown by their high expression of IL-7R and GZMB and low expression of CD49d." (PMID 36705564, 2023). "For instance, the immune receptor killer cell lectin like receptor K1 (NKG2D) activates CD8+T cells and natural killer (NK) cells to stimulate tumor immunity by binding to corresponding ligands on tumor cells." (PMID 37426678, 2023). "In the TCGA dataset, the expression levels of CD2, HAVCR2, HLA-C, HLA-DRA, HLA-E, KLRK1, and TYROBP were all significantly downregulated in tumor tissues compared with para-tumor tissues." (PMID 35794593, 2022). "One major class of genes controlling both activating and inhibitory NK cell receptor groups (NKGs) is Klrc1 [NKG2A], Klrc2 [NKG2C], and Klrk1 [NKG2D] and are involved in specific interactions with the MHC of tumor cells and virally infected cells." (PMID 31009335, 2019). "Within the tumor microenvironment of Cbx3/HP1γ-insufficient mice or wt mice treated with Cbx3/HP1γ-insufficient CD8+ T cells, we detect an increase of Klrk1/NKG2D+ infiltrating CD8+ effector T cells, a concomitant decrease in CD4+ Treg cells." (PMID 28220815, 2017). "In our study, we found the following expression characteristics of KLRK1: the expression levels of KLRK1 in tumor tissues were not consistently higher than those in normal tissues." (PMID 37565867, 2023). "High tumor expression of KLRC1 and KLRC2 were also associated with improved survival in the CGGA LGG patient cohort, but not KLRK1, KLRC2 or KLRC4." (PMID 34539622, 2021).